CAV1 (caveolin 1)
Diseases named in the same sentence as CAV1 in open-access papers (continued):
Sharing a sentence is not in itself a finding about the gene and the disease.
breast carcinoma (continued). "Since the development and progression of breast cancer are dependent on changes in the ECM, we sought to investigate how ECM protein expression and organization are altered in response to the loss of cav-1." (PMID 28187162, 2017). "Previous studies have shown that downregulation of cav-1 in breast cancer has led to cancer invasion and metastasis, poor clinical outcome, altered therapy responses, and decreased progression-free survival time." (PMID 28187162, 2017). "In a coculture system, CAV1−/− fibroblasts were validated to promote breast cancer growth via driving aerobic glycolysis." (PMID 28546853, 2017). "Studies have shown that caveolin-1 can suppress breast cancer and its expression in BC tissue and cells were reduced compared with normal tissues." (PMID 29207674, 2017). "A mutant Cav-1 (P132L) found in scirrhous breast cancer was identified to exert a dominant negative function by cytoplasmic retention." (PMID 29141593, 2017). "A DNA methylation inhibitor restored subdued basal CAV1 expression in colon and breast cancer cells." (PMID 29340103, 2017). "In breast cancer cell lines and melanomas, CAV1 expression favors focal adhesion turnover, cell migration and metastasis." (PMID 29340103, 2017). "The possibility the hypoxia induces degradation of Cav-1 and consequently induces cyclin D1 in the breast cancer stroma remains to be investigated." (PMID 29137220, 2017). "The expression levels of FAP and ACTA2 in putative CAFs from breast tumors were higher than in fibroblasts from normal tissue, whereas CAV1 expression was lower in putative CAFs from breast carcinoma samples than in fibroblasts from normal tissues." (PMID 28596490, 2017). "Recently, enhanced hepatic gluconeogenesis and glucose output were observed in the Cav-1 null mice, and suppressed glycolysis was noted in Cav-1 reconstituted breast cancer epithelial cells, suggesting its implication in glucose metabolism." (PMID 28489581, 2017). "In human breast cancer cell, CAV1 accumulates at invadopodia and its knockdown inhibits invadopodia formation." (PMID 29190968, 2017). "Previous studies have demonstrated that the expression of CAV-1 in both mRNA and protein levels is down-regulated in breast cancer and CAV-1 re-expression can inhibit the growth and the invasive and migratory potential of BC cells." (PMID 29207674, 2017). "Here we show that suppression of basal CAV1 expression in the colon and breast cancer cells employed in our studies is reverted by inhibition of DNA methylation using 5-aza dideoxycytidine." (PMID 29340103, 2017). "Here, we describe Cav1 as an anti-metastatic regulator in mouse models of lung and breast cancer pulmonary metastasis." (PMID 29212030, 2017). "Methotrexate and Etoposide increased mRNA and protein levels of CAV1 in colon and breast cancer cells through activation of the MEK/ERK pathway and the subsequent increase in ROS levels." (PMID 29340103, 2017). "Data on Cav1 expression in CAS from canine mammary tumours is less clear, mainly because studies have mostly focused on staining intensities in the tumour epithelia themselves and not in CAS particularly." (PMID 28531107, 2017). "Taken together, the relationship between Cav-1 and MnSOD appears to have predictive value indicating more invasive forms of breast cancer." (PMID 26543228, 2016). "For example, CAV1 correlates with estradiol-mediated autophagy in the BT474 breast cancer cell line." (PMID 27852311, 2016). "In a luminal breast cancer epithelial cell line devoid of Cav-1 (MCF7) we ectopically expressed Cav-1." (PMID 26543228, 2016). "The results indicate that Cav-1 expression is progressively reduced in breast cancer according to clinical stage and histologic grade and in aggressive breast cancer subtypes." (PMID 26543228, 2016). "Cav-1 protein levels are consistently down-regulated in a wide range of human cancers, including ovarian carcinomas, sarcomas, and mammary carcinomas." (PMID 27611314, 2016).
breast carcinoma (continued). "CAV1 7q31.2 deletions/translocations appear to be downregulated in ovarian, lung, and mammary tumors while upregulated in prostate, bladder, thyroid, and esophageal carcinomas." (PMID 28018857, 2016). "In breast cancer cells, Cav-1 expression is significantly lowered when compared with normal breast tissue." (PMID 25756273, 2015). "Previous reports have suggested a negative regulatory role for caveolin-1 in tumor development in a number of human cancers, and recent studies proved that caveolin-1 inhibits breast cancer cell migration and metastasis." (PMID 26172389, 2015). "Samples from 32 human breast cancer biopsy and normal tissue specimens were evaluated immunohistochemically for caveolin-1 expression." (PMID 26172389, 2015). "Another study indicated that Cav-1 was highly expressed on breast cancer stem cells or side-population cells, which were enriched with ABCG2." (PMID 26431273, 2015). "Cav-1 is known to be overexpressed in aggressive breast carcinomas, and is also correlated with multi-drug resistance." (PMID 25669750, 2015). "Treatment with a DNA methyltransferase inhibitor induces expression of CAV1 through demethylation of CpGi shores in breast cancer cell lines that have low CAV1 expression (even though the CpGi rich promoters are hypermethylated)." (PMID 26112043, 2015). "In a recent report, trastuzumab was demonstrated to colocalize with caveolin-1 in breast cancer cells." (PMID 26172389, 2015). "The expression of the two major endocytic proteins clathrin and caveolin-1 was examined in the breast cancer cell lines, MDA-MB-231, MCF-7, SKBR-3, BT-474, and ZR-75-1." (PMID 26172389, 2015). "Western blotting demonstrated that clathrin and caveolin-1 expression levels differed in these breast cancer cell lines: caveolin-1 was highly expressed in MDA-MB-231 cells." (PMID 26172389, 2015). "HER-2-positive BT-474 and SKBR-3 breast cancer cells that express low and moderate levels of caveolin-1, respectively, were treated with trastuzumab or its conjugate T-DM1." (PMID 26172389, 2015). "Generally, little is known about CAV1 in this type of cancer compared with others, like breast cancer." (PMID 26054531, 2015). "Studies of clinical tissues have shown that breast cancer tissues have hypermethylation of the CAV1 promoter accompanied by down-regulation of CAV1 expression when compared to adjacent normal breast tissues." (PMID 26112043, 2015). "Cav-1 expression was upregulated in inflammatory breast cancer cells and tissues and Cav-1 overexpression significantly contributed to cancer metastasis." (PMID 26431273, 2015). "It has been suggested that inactivation of CAV1 through hypermethylation drives the spread of breast cancer to the lymph nodes." (PMID 26112043, 2015). "A microarray analysis also supported Cav-1 as a metastasis-related gene by comparing gene expression profiles between weakly and highly invasive breast cancer cells." (PMID 26431273, 2015). "Cav-1 overexpression was found in metastatic lesions of breast cancer and was closely correlated with tumor stage and clinical prognosis." (PMID 26431273, 2015). "In ovarian cancer cell lines, treatment with TSA up-regulates CAV1 and in breast cancer cell lines, TSA treatment results in a 35 fold increase in CAV1 expression." (PMID 26112043, 2015). "Systemic rapamycin treatment of mammary tumors grown in Cav-1 KO mice not only inhibited tumor growth but also stromal content and angiogenesis." (PMID 26397134, 2015). "Caveolin-1 limits the contribution of BKCa on breast cancer cell proliferation and invasion by negatively regulating its function and surface expression." (PMID 25397596, 2014). "Collectively, our findings suggest that BKCa is a critical target for suppression by caveolin-1 in suppressing proliferation and invasion of breast cancer cells." (PMID 25397596, 2014).
breast carcinoma (continued). "Given the conflicting information on the expression of Cav-1, at least in breast cancer, GC, hepatic cancer and oral cancer, further studies analyzing the expression of Cav-1 in human cancer cells are warranted." (PMID 25202343, 2014). "Current and future research into mechanisms by which caveolin 1 function in tumorigenesis process will most likely lead to a new molecular marker in diagnosis and prognosis and even in treatment of breast cancer." (PMID 24591761, 2014). "We also demonstrated that caveolin-1 knockdown resulted in activation and increased surface expression of BKCa channels, and subsequently promoted the proliferation and invasiveness of breast cancer cell." (PMID 25397596, 2014). "Together, these results suggested that the caveolin-1 limited the contribution of BKCa channel on breast cancer proliferation and invasion." (PMID 25397596, 2014). "For instance, while CAV1 downregulation is typical for ovarian, lung, and mammary carcinomas, it is upregulated in bladder, thyroid and prostate carcinomas." (PMID 25180681, 2014). "This is consistent with high expression and amplification of the MET gene in human basal breast cancers and amplification of the Met/Cav1 locus in basal-like mammary tumours in mice with mammary-specific deletion of Lfng." (PMID 25200860, 2014). "siRNA mediated caveolin-1 knockdown resulted in activation and increased surface expression of BKCa channel, and subsequently promoted the proliferation and invasiveness of breast cancer cells." (PMID 25397596, 2014). "For example, caveolin-1 was reported to inhibit proliferation, anchorage-independent colony formation and matrix invasion in breast cancer." (PMID 25397596, 2014). "In fact, in a series of studies in vivo researchers found caveolin-1 upregulation in several tumors, such as prostate cancer, lung cancer, and breast cancer." (PMID 25243186, 2014). "In conclusion, our results suggest that caveolin-1 plays an important role in breast cancer proliferation and invasion by regulating the surface expression and activation of BKCa." (PMID 25397596, 2014). "Consistent with previous studies, our findings suggested that caveolin-1 negatively regulate proliferation and invasion in human breast cancer MCF-7 cells." (PMID 25397596, 2014). "We next examined the functional impact of the interaction between caveolin-1 and BKCa channels on breast cancer cells." (PMID 25397596, 2014). "In vitro study has shown that MCF7 (human breast cancer cells) cells exhibit extremely high levels of mitochondrial staining when cocultured with Cav-1 null fibroblasts, as compared with homotypic cultures of MCF7 cells." (PMID 25202343, 2014). "Specifically, increased expression of caveolin-1 inhibits breast cancer growth and invasiveness in both metastatic MDA-MB-231 and non-metastatic MCF-7 breast cancer cells." (PMID 25397596, 2014). "In fact, DNA methylation, has been previously reported to regulate Cav-1 expression in breast cancer and T cell leukemia cell lines." (PMID 24751908, 2014). "This contradictory action of caveolin-1 underscores the complexity and importance of unraveling the mechanism by which it acts as a breast cancer modulator." (PMID 25397596, 2014). "To this end, we chose the human breast cancer MCF-7 cell line that was frequently used in studies about caveolin-1 and BKCa." (PMID 25397596, 2014). "In contrast, over-expression of Cav-1 significantly increases protein levels of IGF-1 receptor in MCF-7 breast cancer cells." (PMID 23472139, 2013).
breast carcinoma (continued). "CAV1 expression levels were clearly different in each breast cancer subtype, higher in BaB subtypes and lower in Lu subtypes." (PMID 23887935, 2013). "Initially, caveolin-1 was regarded as a tumor suppressor because it is downregulated in transformed cells and re-expression of caveolin-1 inhibits colony formation and induces apoptosis in transformed cells and breast cancer cells." (PMID 22505926, 2012). "Here, caveolin-1 participation in metastatic cell migration was evaluated by shRNA targeting of endogenous caveolin-1 in MDA-MB-231 human breast cancer cells and ectopic expression in B16-F10 mouse melanoma cells." (PMID 22505999, 2012). "Decreased expression of cav-1 has also been found in a variety of cancer cell lines of breast carcinoma, colon carcinoma, uterine cervical carcinoma and ovary." (PMID 22200856, 2012). "In vitro studies using a coculture system of the breast cancer cell line MCF7 and fibroblasts have demonstrated that activated autophagy in fibroblasts is the primary cause of fibroblastic Cav-1 degradation." (PMID 23203033, 2012). "The involvement of phosphorylation of caveolin-1 on tyrosine-14 in promoting cell migration is further supported by observations in breast cancer cell lines, including MDA-MB-231 cells." (PMID 22505999, 2012). "In two independent studies Cav-1 expression was found to be lower in human breast cancer cell lines than normal mammary tissue." (PMID 22356861, 2012). "Caveolin-1 is predominantly expressed in invasive breast cancer cell lines and is well correlated with invadopodia activity, implying that caveolin-1 plays important roles in the trafficking of the components of invadopodia including MT1-MMP." (PMID 22253629, 2012). "In this study, we specifically investigated the role of caveolin-1 in metastatic cell migration by employing two different models: MDA-MB-231 human breast cancer cells and the mouse melanoma cell line B16-F10." (PMID 22505999, 2012). "Lisanti’s group analyzed breast tissue samples from 154 women diagnosed with breast cancer using immunohistochemical staining of stromal Caveolin-1." (PMID 22995409, 2012). "Suppression of ErbB2-signaling by lapatinib in ER(−) breast cancer resulted in activation of FOXO3a and caveolin-1, leading to activation of ER-signaling." (PMID 22924092, 2012). "Caveolin-1 has been reported to exist in the invadopodia of human breast cancer cells, and lipid rafts and caveolin-1 reportedly play a key role in invadopodia formation and protease actions within invadopodia." (PMID 22808268, 2012). "Epithelial mammary tumors expressed low levels of Cav-1 while claudin-low mammary tumors expressed much higher levels of Cav-1." (PMID 22356861, 2012). "This pattern of Cav-1 expression was maintained in mammary tumor cell lines derived from MTB-IGFIR transgenic tumors with epithelial or claudin-low characteristics." (PMID 22356861, 2012). "In particular, RBM39, whose expression was increased 6.6-fold by GW9662, was recently reported to be increased in ER-dependent mammary tumors developing in caveolin-1 knockout mice." (PMID 22538444, 2012). "Our findings suggest that Cav-1 expression is dependent of the subtype of mammary tumor being investigated." (PMID 22356861, 2012). "In our MTB-IGFIR transgenic model, Cav-1 was found to be expressed in adipocytes and smooth muscle cells in the mammary gland but the cells of mammary tumors induced by IGF-IR overexpression expressed considerably less Cav-1." (PMID 22356861, 2012). "It appears that epithelial mammary tumors express low levels of Cav-1 but mammary tumors that acquire claudin-low characteristics express Cav-1." (PMID 22356861, 2012). "Cav-1 was significantly downregulated (~37-fold) in the mammary tumor tissue compared to normal mammary tissue." (PMID 22356861, 2012).
breast carcinoma (continued). "Overexpression of cav-1 has been shown to be associated with ECM degradation and formation of invadopodia, which contain membrane-type-1-MMP (MT1-MMP) and mediate breast cancer cell motility and invasion." (PMID 21199580, 2011). "In IBC patient tissues and cell lines, cav-1 is overexpressed, a phenotype observed in other aggressive breast carcinomas that show high metaplastic properties." (PMID 21199580, 2011). "In fact, re-expression of CAV1 has successfully reduced the tumor growth of breast cancer cells and the invasive capability of pancreatic and breast cancer cells." (PMID 21471610, 2011). "We selected five genes (CAV1, DHFR, TYMS, VIM, ZEB1) known to be associated with drug sensitivity and the epithelial-mesenchymal transition of breast cancer." (PMID 21501481, 2011). "Although the role of cav-1 in breast cancer is contradictory, overexpression of cav-1 is present in aggressive types of breast cancer such as metaplastic carcinoma and IBC." (PMID 21199580, 2011). "More recent data suggest that high expression of caveolin-1 is a characteristic of triple-negative and other basal-like breast cancers, including IBC of a basal phenotype." (PMID 22093547, 2011). "More specifically, thetranscriptional profiles of Cav-1 (-/-) stromal cells were most closely relatedto the stroma of breast cancer patients that had undergone LN-metastasis." (PMID 20442453, 2010). "Earlier studies have implicated the androgen receptor (AR) in human prostate cancer cells and the progesterone receptor (PR) in breast cancer cells as stimulators of caveolin-1 expression." (PMID 20098621, 2010). "We previously demonstrated that Cav-1- regulated calcium homeostasis plays a role in growth and survival of breast cancer cells." (PMID 20700465, 2010). "Using an unbiased informatics analysis of transcriptionalgene profiling, we show that Cav-1 (-/-) stromal cells bear a striking resemblanceto the activated tumor stroma of human breast cancers." (PMID 20442453, 2010). "Here, we used an unbiased informaticsanalysis of transcriptional gene profiling to show that Cav-1 (-/-)bone-marrow derived stromal cells bear a striking resemblance to theactivated tumor stroma of human breast cancers." (PMID 20442453, 2010). "More specifically, thetranscriptional profiles of Cav-1 (-/-) stromal cells were most closelyrelated to the primary tumor stroma of breast cancer patients that hadundergone lymph-node (LN) metastasis." (PMID 20442453, 2010). "Rather caveolin-1 staining was readily detected in metaplastic breast cancers and to a lesser extent in invasive breast cancers." (PMID 18400052, 2008). "In contrast, it has been suggested that Cav-1 acts as a putative tumour and metastasis suppressor of breast cancer, indicating that the role of Cav-1 in metastasis is cell-type specific and remains to be defined." (PMID 19002186, 2008). "Cav-1 has been reported to suppress cell transformation and its absence promotes early steps in mammary tumor formation in mice." (PMID 18811984, 2008). "Further studies are warranted to understand the role of Caveolin-1 expression in the disease course of breast cancer as well as its potential as a therapeutic target." (PMID 17915016, 2007). "They described a significant positive correlation between Caveolin-1-mRNA expression in breast cancer and positive oestrogen receptor-status as well as reduced tumour size." (PMID 17915016, 2007). "Based on a cutoff score of ≥ 4 they reported Caveolin-1 expression in 9.4% of primary breast cancers." (PMID 17915016, 2007). "Caveolin-1 expression is reduced in early mammary carcinogenesis, but increased levels have been found in many basal-like breast cancers." (PMID 17764562, 2007). "We further examined the distribution of Caveolin-1 expression among distinct histological subtypes of breast cancer." (PMID 17915016, 2007). "Correlation analysis of Caveolin-1 expression with clinical and pathological variables in primary breast cancer patients." (PMID 17915016, 2007).